SNORA58 (small nucleolar RNA, H/ACA box 58)
Synonyms: ACA58; SNORA58B
Gene: Small nucleolar RNA gene on chromosome 3 (131,479,097 to 131,479,233, reverse strand). Ensembl gene ENSG00000249020.
Gene Ontology:
Biological process: RNA processing
Cellular component: nucleolus
Homologues: Orthologues: chimpanzee SNORA58 (99% identical), macaque SNORA58 (97% identical), mouse Gm54509 (80% identical), rat Gm50450 (80% identical). Paralogues in human: SNORA58B (87% identical).
Diseases named in the same sentence as SNORA58 in open-access papers:
SNORA58 is named in the same sentence as 2 diseases in open-access papers, as found by Europe PMC text mining. Sharing a sentence is not in itself a finding about the gene and the disease. The quoted sentences say what the papers report.
tumor (2 papers, 2019 to 2025). "We found eight snoRNAs (ACA47, E2, ACA10, SNORA58, HBII-316, U70, U8, and U66) that were upregulated in tumor compared with normal tissues (P < 0.05)." (PMID 31552164, 2019).
SNORA58 also shares sentences with these, for which no sentence is quoted: gastric cancer (1 paper).